IL9 (interleukin 9)
Diseases named in the same sentence as IL9 in open-access papers (continued):
Sharing a sentence is not in itself a finding about the gene and the disease.
tumor (continued). "In this report, we provide data to support a model where IL-9 promotes tumor growth in the lung through macrophages." (PMID 35778404, 2022). "Although IL-9 has potent anti-tumor activity in adoptive cell transfer therapy, some models suggest that it can promote tumor growth." (PMID 35778404, 2022). "Remarkably, anti-IL9 treatment was even effective in mice with already established lesions in both models suggesting a key function role of IL-9 in controlling tumor growth in vivo." (PMID 35514957, 2022). "Th9 cells and other IL-9 producers can have anti-tumor effects through both IL-9-dependent- and -independent mechanisms." (PMID 35778404, 2022). "As these findings suggested the possibility that IL-9 induces IL-9R expression in intestinal epithelial cells, we next determined the functional effects of IL-9 signalling on IL-9R expression by in vitro studies using tumour organoids." (PMID 35793807, 2022). "IL-15, a type I cytokine together with IL-2, IL-4, IL-7, IL-9, and IL-21, promotes survival of T, B, and NK cells by binding to IL-15α, encoded by IL15RA, negatively regulating both carcinogenesis and tumor growth." (PMID 36432658, 2022). "The serum levels of both IL-9 and IL-27 were significantly higher in the probiotic group compared with the model group, which potentially played a role in inhibiting tumor growth." (PMID 36615662, 2022). "Consistent with the reported IL-9 anti-tumor activity, F8IL9F8 treatment resulted in mild tumor growth delay in murine models of melanoma and colon cancer." (PMID 33801620, 2021). "IL-9 derived from Th9 cells can improve the tumor killing function of CD8+ T cells and NK T cells by promoting secretion of IFN-γ." (PMID 34386015, 2021). "Here, we reviewed our current understanding of the role of IL-9 in several neoplasias, and pointed out that it exerts protective activities on solid tumors while acting as a pro-tumoral soluble factor in hematologic malignancies." (PMID 34944921, 2021). "Immunization of B16F10-OVA tumor-bearing mice with dectin-1-activated DCs induced potent antitumor response that was dependent on induction of Th9 cells and IL-9 production." (PMID 33748292, 2021). "Paradoxically, in muscle-invasive bladder cancer patients, higher infiltration of IL-9+ cells in the tumor tissue correlated with impaired cytotoxic function of CD8+ T cells and NK cells, higher frequencies of Treg cells, and poor prognosis." (PMID 33777008, 2021). "Tc9 cells, a subset of CD8+ T cells that highly express IL-9, have stronger anti-tumor ability than Tc1 cells." (PMID 34742349, 2021). "Depending on the milieu, MCs represent a source of either pro-tumorigenic factors favoring angiogenesis and tumor growth or anti-tumorigenic molecules (TNFα and IL-9) with a protective function." (PMID 34282774, 2021). "The current idea is that IL-9 exerts opposite effects on tumor development according to the type of neoplastic cell and to its microenvironmental niche." (PMID 34944921, 2021). "Th9 cells and secreting IL-9 contributed to the functional regulation of mast cells and regulatory T cells, which have been demonstrated to inhibit immune response and promote tumor development in hematological malignancies." (PMID 34177894, 2021). "A recent study also confirmed the antitumor effect of IL-9, demonstrating that overexpression of IL-9 inhibited tumor growth in vivo." (PMID 35008550, 2021). "IL-9-producing T cells and IL-9 secretion contributes to tumor immunity and immune-related diseases, which provides useful insight into pathogenesis and treatment." (PMID 34177894, 2021). "IL-9 has both anti- and pro-tumor actions that are not well understood, and IL-9 has complicated anti-tumor and pro-tumor properties mediated by innate and adaptive immunity, including in PCa." (PMID 34604038, 2021). "Indirect interactions between tumor cells and MCs caused by soluble factors produced by HRS cells, such as IL-9, IL-13, CCL5/RANTES are important for MC infiltration and proliferation." (PMID 34631562, 2021).
tumor (continued). "Splenocytes from mRIPO-treated animals provoked varied tumor-specific lymphocyte states as evidenced by expanded baseline and antigen-specific Th1- (IFNγ, TNF), Th2- (IL-5), and Th9- (IL-9) associated cytokine secretion." (PMID 33767151, 2021). "Referring to the results after the Backward Stepwise selection method (the final multivariable Cox proportional hazards model), only three significant predictors remained: tumour size (T), metastasis to the neck lymph nodes, and IL-9 rs1859430 AA genotype." (PMID 33803218, 2021). "Th9 cells, which are significantly increased in the peripheral blood of breast cancer patients, act via the secretion of both IL-9 and IL-21, which promotes cytotoxicity of tumor-specific CTLs." (PMID 34944921, 2021). "Beside playing a regulatory role in autoimmunity and allergic reactions, IL9 has been suggested to be involved in anti-parasitic and anti-tumor responses, and in the formation of immune tolerance." (PMID 33801620, 2021). "Irrespective of the cells involved in the secretion of this cytokine, the increased amount of IL-9 in the CLL tumor microenvironment has been proven to promote tumor development." (PMID 34944921, 2021). "The addition of cholesterol-derived oxysterols inhibits IL-9 expression, induces apoptosis of Tc9 cells, and results in impaired anti-tumor activity." (PMID 34742349, 2021). "IL-33 treatment also drove the induction and cytotoxic activities of DC-induced Tc9 cells, a subset of effector CD8+ T cells producing cytotoxic IL-9, and further promoted the therapeutic efficacy of DC-based tumor vaccines." (PMID 34209038, 2021). "Among the immunotherapies tested, IFNα was more effective than anti-PD-L1, anti-CTLA-4, anti-4-1BB, IL-2, and IL-9 in reducing Myc-CaP CRPC tumor growth." (PMID 34771735, 2021). "Th9 cells fight against tumors thanks to their ability to secrete high amounts of IL-9, as demonstrated by the fact that IL-9 deletion abolishes the Th9-mediated anti-tumor effects." (PMID 34944921, 2021). "Blocking the IL-9/Jak3 pathway has potential for treatment of both ALK+ ALCL and BIA-ALCL where tumor cells express IL-9 in an autocrine loop." (PMID 34503066, 2021). "An exception is represented by metastatic lung cancer, a solid tumor where Th9 and Th17 lymphocytes induce metastatic spreading through IL-9 secretion, thereby strongly favoring tumor metastasis." (PMID 34944921, 2021). "Tumor-infiltrating CD4+T cells isolated from the Sirt1flox/floxCd4-Cre mice displayed higher IL-9 production and IL9+ ratio accompanied by higher glycolytic activity, compared with CD4+T cells isolated from WT." (PMID 33748292, 2021). "IL-9 not only induces innate and adaptive immune responses but also directly promotes tumor apoptosis." (PMID 34771735, 2021). "Given the physiological importance of IL-9, particularly in anti-tumor immunity, a detailed understanding of molecular regulation of IL-9 induction in Th cells is needed." (PMID 34075041, 2021). "As opposed to solid tumors, where IL-9 acts as a protective soluble molecule in the tumor microenvironment, IL-9 mainly exerts a pro-tumoral effect in hematologic malignancies." (PMID 34944921, 2021). "Originally identified as a mediator of allergic responses, IL-9 has been detected in recent years in several tumor niches." (PMID 34944921, 2021). "We therefore injected either recombinant IL-9 or PBS in ABX-treated mice throughout tumour development, and found enhanced tumour control in IL-9-treated animals, as shown by a lower number of lung foci compared with animals treated with PBS." (PMID 32499569, 2020). "Increased IL-9 promotes tumor-specific cytotoxic T lymphocytes and tumor regression by enhancing the function of DCs." (PMID 32228589, 2020). "IL9 is a cytokine released from the CD4 subset of Th9 cells that is involved in the anti-tumor response." (PMID 32483272, 2020).
tumor (continued). "Animal experiments show that the growth of the tumor is greatly inhibited when tumor-specific Th9 cells are administered, and this effect can be revered by anti-IL-9." (PMID 32228589, 2020). "IL-9 knockout mice exhibit strong tumor cell growth inhibition and have more normal activated CD4+ and CD8+ T-lymphocyte production than control mice." (PMID 32228589, 2020). "Th9 cells are the most studied IL-9-producing cells in tumor immunity, and almost all reports show that Th9 cells play an antitumor role." (PMID 32228589, 2020). "We found that faecal transplant is sufficient to restore intestinal microbiota diversity and the frequency of IL-9-producing T cells in the lungs of antibiotic-treated animals, restraining tumour burden." (PMID 32499569, 2020). "Tregs recruit mast cells into tumor site via secretion of IL-9 by themselves under stimulation of mast cell, meanwhile, IL-9 maintains the immunosuppressive ability of Tregs and promote tumor progression." (PMID 32508809, 2020). "The role of IL-9 is paradigmatic because it can either promote tumor progression in hematological malignancies or inhibit tumorigenesis in solid cancers." (PMID 33488574, 2020). "Through immunofluorescence staining of 143 tumor tissues of EC patients, we found that nearly all the Vδ2 + γδT cells were IL9 positive." (PMID 33329510, 2020). "Its action in cell proliferation and in the programmed cell death of tumor cells indicates its role in tumor evolution, even if IL-9 has opposite effects according to the type of neoplastic cell." (PMID 32102441, 2020). "In cutaneous T cell lymphoma (CTCL), STAT3/5-dependent IL-9 overexpression promotes tumor cell survival." (PMID 32228589, 2020). "Recently, we20–23 and others have shown that antigen-specific IL9-secreting (CD4+ Th9 or CD8+ Tc9) T cells are distinct subsets with stronger antitumor efficacy in murine tumor models compared to Th1, Th17, or Tc1/CTLs, respectively." (PMID 33214555, 2020). "Recently, the roles of IL-9- and IL-9-producing cells in tumor immunity have attracted increasing attention." (PMID 32228589, 2020). "We evaluated the plasma concentrations of Th1 (IL-2, IFN-γ, and TNF-α), Th2 (IL-4, IL-5, IL-6, and IL-10), Th9 (IL-9), and Th17 (IL-17A, IL-17F, IL-21, and IL-22) cytokines in tumor-bearing mice by flow cytometry." (PMID 32802733, 2020). "Foxo1 induces the differentiation of IL-9-derived Th9 cells, while Foxp1 plays an inhibitory role in Th9 cells differentiation, providing a promising target for anti-tumor immunotherapy." (PMID 32228589, 2020). "The anti-tumor effect of conventional Th9 cells induced under IL-4 plus TGF-β treatment was dependent on IL-9." (PMID 32508847, 2020). "Overall, these data indicate that antibiotic-mediated dysbiosis negatively modulates IL-9-producing T cells in the tumour microenvironment, and that antibiotic-treated animals are more susceptible to tumour development." (PMID 32499569, 2020). "Researchers have found that the levels of IL-4, IL-10, VEGF and TGF-β are decreased in IL-9-treated tumor-bearing nude mice." (PMID 32228589, 2020). "STAT5 and BATF convert Th17 cells into cells that mediate IL-9-dependent effects in allergic airway inflammation and anti-tumor immunity." (PMID 32985505, 2020). "We also performed long-term antibiotic treatment in specific pathogen-free mice to evaluate the impact of host dysbiosis on IL-9-producing T cells in the colonic lamina propria, and in the context of extraintestinal tumour immunity." (PMID 32499569, 2020). "While some studies claimed that IL-9 inhibits tumor growth both in vivo and in vitro, others have found that IL-9 increases proliferation in some tumor cell lines and its absence contributes to the early rejection of transplanted tumor cells in vivo." (PMID 33371444, 2020). "IL-9 was first identified as a growth factor for T-lymphocytes, mast cells, and hematopoietic tumor cells." (PMID 32102441, 2020).
tumor (continued). "The main idea is that IL-9, as a lymphocyte growth factor, can promote tumor progression in hematological tumors, while in solid tumors, IL-9 can inhibit tumor development by activating innate or adaptive immune responses." (PMID 32228589, 2020). "This demonstrates that IL-9 can negatively regulate T cell function and participate in tumor progression." (PMID 32228589, 2020). "Faecal transplant restores intestinal microbiota diversity, and the frequency of IL-9-producing T cells in the lungs of dysbiotic animals, restraining tumour burden." (PMID 32499569, 2020). "The viewpoint of Dominique Bet al. in this paper is different from common opinion of IL-9 in tumor immunity." (PMID 32228589, 2020). "IL-9 can directly affect the survival of tumor cells, or indirectly participate in tumor immunity by activating mast cells and recruiting dendritic cells (DCs) into tumor sites." (PMID 32228589, 2020). "Glucocorticoid-induced tumor necrosis factor receptor (GITR) can promote tumor regression by inducing the production of IL-9-producing CD4+ T cells." (PMID 32228589, 2020). "GM-CSF-activated monocyte-derived dendritic cells convert tumor-specific naïve Th cells into Th9 cells and delay tumor growth by inducing antitumor CTLs in an IL9-dependent manner." (PMID 33271839, 2020). "report low IL-9 amounts in CRC patients, but these low levels are associated with tumor progression." (PMID 33488574, 2020). "Here, we review recent studies on IL-9 and several kinds of IL-9-producing cells in tumor immunity to provide useful insight into tumorigenesis and treatment." (PMID 32228589, 2020). "The number of IL-9-producing Th9 cells is significantly increased in the circulation and tumor tissue of HCC patients, and the more Th9 cells there are, the shorter the survival rate of HCC patients." (PMID 32228589, 2020). "More importantly, the inhibitory effect of IL-9 on the adaptive immune response can destroy the sensitivity of host T cells to tumor cells." (PMID 32228589, 2020). "In fact, we show—for the first time in human CRC—that Prevotella and Bacteroides species are correlated positively and negatively, respectively, with the IL-9 that has an intriguing and still debated role in tumor immunity." (PMID 33488574, 2020). "IL-9 not only exerts a tumorigenic role in the hematological tumors and in some solid tumors but also has tumor-promoting ability." (PMID 32228589, 2020). "Th9 cells that are mainly characterized by the secretion of IL-9, have protective roles against parasite infections and tumor development." (PMID 31156634, 2019). "Then, we detected Fas and IL-9 expression in CD4+ T cells from tumor tissues in a cohort of 36 cancer patients with non-small-cell lung carcinoma (NSCLC)." (PMID 31266950, 2019). "We found that the tumor progression in the Faslpr → WT mice was superior to that in the WT → WT mice, which was IL-9 dependent." (PMID 31266950, 2019). "In vivo, IL-9 overexpression significantly inhibited tumor growth and resulted in a longer survival time in a mouse subcutaneous allograft model." (PMID 31637216, 2019). "IL-9 at D3 and D7 seemed to be related to anti-tumor effect and IL-6 at D7 and D60, and IL-22 at D60 was related to regenerative but not pro- or anti- inflammatory function." (PMID 31751357, 2019). "Collectively, these results demonstrated that Fas signaling also promotes human IL-9-producing T cell induction, which has a beneficial effect on the outcomes of patients with tumor." (PMID 31266950, 2019). "Further analysis confirmed the positive correlation between the numbers of Fas+CD4+ T cells and IL-9+CD4+ T cells in the tumor tissues." (PMID 31266950, 2019). "On D7, IL-6 and IL-9 were isolated from the network, which seemed to have regenerative function and anti-tumor effect, respectively." (PMID 31751357, 2019).
tumor (continued). "We further demonstrated in the current study that the DCG administration results in increased levels of IFNγ/IL-10 in the spleen and increased IFNγ/IL-9 secreting T cells infiltrating to the tumour site." (PMID 31183361, 2019). "IL-9 activates innate immune cells like mast cells, contributing to tumor growth prevention, and in addition to Th9 cell-derived IL-3, induction of adaptive anti-cancer responses that favor DCs survival has been reported in various cancers." (PMID 31861351, 2019). "The role of IL-9 in tumor immunity has been controversial, both promoting antitumor immunity and enhancing transformation and tumor growth." (PMID 30842774, 2019). "The number of Fas+CD4+ T cells and IL-9+CD4+ T cells in tumor tissues was positively correlated, and higher TH9 cell numbers in patients with tumor indicated a better prognosis than lower TH9 cell numbers." (PMID 31266950, 2019). "Taken together, the DCG spore treatment increases the levels of proinflammatory cytokines at the tumour site and attracts IFNγ/IL-9 secreting T cells to the tumour." (PMID 31183361, 2019). "Intravenous administration of the derivative of Clostridial ghonii (DCG) spores leads to both tumour and systemic inflammatory responses characterized by increased IFNγ/IL-9 secreting T cells in the spleen and the tumour." (PMID 31183361, 2019). "Calcitriol or its analogues downregulated the expression of 4 genes related to the Th1 response in tumour tissue (Ifng (only calcitriol), Socs1, Tbx21 and Fasl) and upregulated 5 genes related to the Th2 response (Ccl11, Ptgdr2, Il9, Asb2 and Il5)." (PMID 31595196, 2019). "Th9 cells promote the activation of adaptive anti-tumor immune responses via IL-9 secretion, which activates mast cells that exhibit tumor growth-preventing activities." (PMID 31216735, 2019). "Although IL-9 can be produced by many cell types within the context of pathogen immunity, tumor immunity, and inflammatory disease, the regulation of this cytokine is still largely uncharacterized." (PMID 30442929, 2018). "They observed following adoptive transfer into tumor-bearing mice that TH9 cells maintained their IL-9 and IL-10 production in the tumor-draining lung lymph node (LLN) without switching to IFN-γ or IL-17 producers." (PMID 27832300, 2017). "Conversely, injection of recombinant IL-9 protein into wild-type mice impaired B16 tumor cell growth in vivo." (PMID 27832300, 2017). "By analysing the B16-OVA tumour infiltrate, we found enhanced frequency of IL-9-producing CD4 tumour-infiltrating lymphocytes (TILs)." (PMID 28916785, 2017). "TH9 cells have an important role in tumor immunity that seems to be largely due to their ability to secrete IL-9 and IL-21 cytokines." (PMID 27832300, 2017). "Our results suggest that in the tumour microenvironment TH9 cells undergo increased autophagy leading to decreased IL-9 expression." (PMID 28916785, 2017). "While IL-9 promotes the activation of innate immune cells like mast cells, which can then contribute to tumor growth prevention, other studies clearly suggest that the anti-tumor activity of IL-9 is not only due to the activation of innate immune effectors." (PMID 27832300, 2017). "They next identified TH9 cells as the major source of IL-9 in this tumor model in response to DTA-1 treatment." (PMID 27832300, 2017). "In contrast, injection of recombinant TGF-β into the tumour increased both IL-9-eGFP+ CD4+ T cells and Irf8 expression in CD4+ T cells in vivo." (PMID 29233972, 2017). "Overall, these results illustrate that TH9 cells can enhance mast cell activity through IL-9 secretion, resulting in tumor growth prevention." (PMID 27832300, 2017). "We and others have found that Th9 cells also exert an indirect anti-tumour effect resulting from secretion of IL-9 and IL-216–8." (PMID 29233972, 2017). "IL-9 is a pleiotropic cytokine that can have direct anti-tumor effects or can indirectly influence tumor growth by enhancing immune responses." (PMID 27832300, 2017).